FZD7 (frizzled class receptor 7)
Diseases named in the same sentence as FZD7 in open-access papers (continued):
Sharing a sentence is not in itself a finding about the gene and the disease.
hepatocellular carcinoma (continued). "miR-144-3p was significantly downregulated in hepatocellular carcinoma, glioblastoma, multiple myeloma and pancreatic cancer and inhibited proliferation, migration and tumour metastasis by targeting SGK3, FZD7, c-Met and FOSB." (PMID 31552107, 2019). "SOX8 and SOX9 induced the FZD7-mediated activation of the WNT/β-catenin pathway to regulate chemoresistance, stem-like properties and EMT in tongue squamous cell carcinoma (TSCC) and hepatocellular carcinoma (HCC)." (PMID 29789460, 2018). "In hepatocellular carcinoma, upregulation of FZD7 was positively correlated with nuclear accumulation of wild-type β-catenin, and interaction between WNT3 and FZD7 could lead to activation of canonical WNT signaling pathway." (PMID 29029485, 2017). "ABCB6, IPO7, TIMM9, FZD7, and ACAT1, the five HBV-related genes that affect the prognosis, can work as reliable biomarkers for the diagnosis of Hepatocellular carcinoma, giving a new insight for improving the prognosis, diagnosis, and treatment outcomes of HBV-type Hepatocellular carcinoma." (PMID 36685852, 2022). "In hepatocellular carcinoma (HCC) cells, CR-1 binds and stabilizes DVL3, helped by the concomitant binding of the Frizzled receptor FZD7 and the transmembrane lipoprotein LRP6, resulting in a more sustained signal from the Wnt/β-catenin axis." (PMID 34360603, 2021). "Rhodamine-tagged heptapeptide protein transduction domain for binding DVL (RHPDs) are small interfering peptides that disrupt the binding of FZD7 and the PDZ domain of DVL and were able to inhibit tumor growth in a mouse model of hepatocellular carcinoma (HCC)." (PMID 35204808, 2022).
ovarian carcinoma (30 papers, 2016 to 2026). A malignant neoplasm originating from the surface ovarian epithelium. "FZD7 has been implicated in tumor aggressiveness through the Wnt/PCP pathway in ovarian cancer, and its upregulation during melanoma progression suggests a role in inducing tumorigenesis and tumor growth by WNT11-FZD7-DAAM1 signaling." (PMID 41531533, 2025). "For example, frizzled family receptor 7 (FZD7), a receptor for Wnt signaling, is associated with aggressiveness in Stem‐A ovarian cancer by casein kinase 1ɛ‐mediated non‐canonical Wnt/PCP pathway." (PMID 38045829, 2023). "In addition, in ovarian cancer, FZD7 marks a cell population that is highly susceptible to ferroptosis." (PMID 37091799, 2023). "Studies have revealed that FZD7 gene expression often increases when ovarian cancer tissues are resistant to platinum-based drugs." (PMID 39931061, 2025). "In ovarian cancer tissue, FZD7 can activate the carcinogen P63, enhance the expression of GPX4, prevent tumor cell ferroptosis, and decrease the susceptibility of drug-resistant ovarian cancer cells to ferroptosis." (PMID 39192972, 2024). "Zhang demonstrated that miR-1-3p binds to the 3′UTR site of FZD7 and reduces FZD7 expression in ovarian cancer cell lines." (PMID 38793064, 2024). "Platinum-resistant ovarian cancer cells and tissues are more likely to form spheroids and have increased level of the Wnt receptor frzzled 7 (FZD7)." (PMID 39396974, 2024). "As a tumor suppressor, miR-1-3p obstructs cell proliferation, migration, and invasion, restricting the expansion of ovarian cancer cells by targeting crucial genes involved in cell cycle progression, such as c-Met and FZD7." (PMID 38793064, 2024). "Elevated expression of Frizzled 7 (FZD7) was correlated with platinum resistance in ovarian cancer cells partially due to the decreased ferroptosis regulated by the FZD7/Tp63/GPX4 signaling axis." (PMID 36926345, 2023). "A Wnt signaling receptor, FZD7, has been shown to be critical for anoikis resistance in ovarian cancer." (PMID 36925640, 2023). "Ming Tan identified that the FZD7-TWIST1 axis is critical for ovarian carcinoma tumorigenesis and anoikis resistance." (PMID 36123378, 2022). "Recently, it has been shown that FZD7 regulates spheroid proliferation in ovarian cancer stem cells (CSCs)." (PMID 30548372, 2019). "We found that FZD7 expression was crucial to the maintenance of the mesenchymal phenotype, anoikis resistance, and spheroid and tumor formation in ovarian cancer (OC)." (PMID 30548372, 2019). "Previous studies have found that ferroptosis is involved in the regulation of platinum‐resistant ovarian cancer cells, and the survival of the platinum‐resistant cell population marked by frizzled transmembrane receptor 7 (FZD7) depends on the FZD7/ β‐catenin /Tp63/GPX4 signaling pathway." (PMID 40821694, 2025). "This shows that treating ovarian cancer cells resistant to platinum may benefit from targeting FZD7." (PMID 39192972, 2024). "In addition, miR-1-3p significantly improves the sensitivity of ovarian cancer cells to Erastin or RSL3-induced ferroptosis by decreasing FZD7 expression." (PMID 39192972, 2024). "Recent studies have shown that FZD7 could promote ferroptosis through β-catenin-TP63-GPX4 pathway in ovarian cancer." (PMID 37060074, 2023). "Particularly, it was shown that the overexpression of a receptor of the Wnt signaling pathway, the Frizzled family receptor 2 (FZD7) in the Stem A subtype: in vitro experiments support a role for FZD7 in driving the aggressiveness of Stem A subtype ovarian cancer cells." (PMID 29389895, 2018). "FZD7 is upregulated in the Stem-A subgroup of ovarian cancer, which has a poor clinical outcome." (PMID 27196929, 2016). "Interestingly, inhibition of FZD7 in ovarian cancer cells resulted in an increase in the level of canonical signalling, whilst the non-canonical signalling components including RhoA were slightly down regulated." (PMID 27196929, 2016).
ovarian carcinoma (continued). "Therefore, it is applicable to explore whether FZD7 could be used as a novel biomarker to evaluate the sensitivity of platinum-resistant ovarian cancer cells to ferroptosis." (PMID 36090052, 2022). "Previous studies showed that FZD7 might drive aggressiveness in Stem-A Ovarian cancer by regulating cell proliferation, cell cycle progression, maintenance of the Mesenchymal phenotype and cell migration via casein kinase 1-mediated non-canonical WNT/PCP pathway." (PMID 29029485, 2017). "Levels of FZD7 were higher in MDA-MB-231 than in MA-148, an ovarian cancer cell line that we used previously to demonstrate ADC killing in vitro and in vivo." (PMID 41218118, 2025). "Genes significantly downregulated by ALDH1A1 inhibition included stem cell markers (CD44, FZD7, and SOX9) and genes involved in chemoresistance (ABCB1 and NFκB) in ovarian cancer." (PMID 35884498, 2022). "The ovarian cancer cell line OVCAR5, after FZD7 knockdown, is highly sensitive to ferroptosis." (PMID 40821694, 2025). "Moreover, its aggressiveness in ovarian cancer has been attributed to the activation of non-canonical Wnt/PCP pathway through FZD7." (PMID 38612653, 2024).
gastric cancer (26 papers, 2008 to 2025). A primary or metastatic malignant neoplasm involving the stomach. "Specifically, FZD7 is overexpressed in various solid cancers and high levels of FZD7 associate with shorter survival of colorectal and gastric cancer patients." (PMID 27409829, 2016). "For example, FZD7 regulates stem cell activity in the gastric and intestinal epithelium, with its expression increasing in gastric cancer cells." (PMID 40444048, 2025). "For example, in gastric cancer progression, mutated YTHDF1 enhances the expression of the key oncogenic factor Wnt receptor Frizzled7 (FZD7), leading to gastric cancer progression and poor prognosis." (PMID 35707365, 2022). "In gastric cancer, FZD7 promotes EMT through canonical WNT signaling and silencing of FZD7 inhibits EMT." (PMID 34604862, 2021). "Subsequent analysis demonstrates FZD7 to be negatively regulated by miRNA-27b, which when overexpressed is sufficient to inhibit the expression of FZD7 and reduce gastric cancer cell proliferation." (PMID 27196929, 2016). "However, in colorectal and gastric cancers, FZD7 is overexpressed, amplifying β-catenin signaling to sustain tumor growth and resistance to therapy." (PMID 40376615, 2025). "Fzd7 has been proposed as a novel stem cell-specific receptor with an important role in embryonic stem cell self-renewal capacity and chemo-resistance of gastric cancer side population cells." (PMID 38822429, 2024). "In addition, research has shown that FZD7 is up-regulated in gastric cancer, esophageal cancer, and HCC, and is the target gene of tumor-suppressive miRNA miR-504." (PMID 36685852, 2022). "Similarly, in gastric cancer, mutated YTHDF1 enhances the translation of FZD7 to activate the Wnt-β-catenin pathway to promote gastric cancer cell proliferation and tumorigenesis." (PMID 33795663, 2021). "Aberrant activation of FZD7 has been found in several types of cancer such as breast, colorectal, hepatocellular carcinoma, and gastric cancer." (PMID 30548372, 2019). "It is reported that Helicobacter pylori infection promotes FZD7 expression in gastric cancer cells." (PMID 29789460, 2018). "Indeed, conditional deletion of Fzd7 is able to inhibit the growth of gastric cancer cells and in mouse models of GC and colony forming assays with human GC cells." (PMID 27196929, 2016). "Likewise, targeted knockdown (siRNA) of FZD7 in H. pylori-induced gastric cancer cells effectively phenocopies the effect of miRNA-27b overexpression." (PMID 27196929, 2016). "Knockdown of FZD7 inhibited metastasis and EMT in cervical cancer cells and gastric cancer cells, and suppressed tumor transformation in triple negative breast cancer (TNBC) cell lines MDA-MB-231 and BT-20." (PMID 29789460, 2018). "FZD7 was found to be up-regulated in the gastric cancer cell line MKN7 and in a case of primary gastric cancer." (PMID 26675214, 2015). "In certain cancers, such as gastric cancer and melanoma, noncanonical signaling of FZD7 can also contribute to cancer phenotypes." (PMID 40376615, 2025). "Consistent with this, a potent anti-tumor effect was demonstrated by blocking FZD7 function in gastric cancer cells with and without mutant APC." (PMID 32486480, 2020). "In this study, we tested the hypothesis that the response to neoadjuvant/perioperative chemotherapy correlates with the expression of four different putative cancer stem cell markers of gastric cancer (GC), i.e., LGR5, FZD7, TROY, and MIST1." (PMID 31827644, 2019). "This is partially in line with the study in gastric cancer cells, although no increase of H3K9me3 was observed after FZD7 knockdown." (PMID 30548372, 2019). "RHOA, a downstream component of non-canonical Wnt signalling and FZD7, is upregulated in GC, whilst ROR1, a tyrosine kinase like receptor able to transmit non-canonical Wnt5a signals, is phosphorylated in HS746T human gastric cancer cells, via a Met dependant mechanism." (PMID 27196929, 2016).
colorectal cancer (23 papers, 2009 to 2025). A primary or metastatic malignant neoplasm that affects the colon or rectum. "In colorectal cancers, mutations in kinases or phosphatases that regulate this phosphorylation can lead to aberrant stabilization of FZD7, contributing to excessive Wnt/β-catenin activity and tumor proliferation." (PMID 40376615, 2025). "Fzd7 overexpression is highly associated with advanced tumor stages in gastric and colorectal cancers, although the studies reporting these finding were performed using human tumor tissues and in vitro culture systems." (PMID 36691900, 2023). "FZD7 encodes a cell-surface Wnt receptor in intestinal stem cells, which has been linked to colorectal cancer." (PMID 32403323, 2020). "Overexpression of FZD7 has also been reported to be significantly associated with tumor cell proliferation in colorectal cancer and glioma." (PMID 29029485, 2017). "Fzd7 can activate Wnt/β-catenin signaling in colorectal cancer cells despite the presence of APC or CTNNB1 mutations." (PMID 29207657, 2017). "For example, CRISPR-mediated knockdown of FZD7 has reduced Wnt/β-catenin signaling in preclinical colorectal cancer models, highlighting the potential for gene-editing approaches in targeting FZD-driven oncogenesis." (PMID 40376615, 2025). "For example, studies using live-cell imaging have shown that aberrant recycling of FZD receptors, such as FZD7, sustains hyperactive Wnt signaling in colorectal cancer, driving tumor proliferation and resistance to therapy." (PMID 40376615, 2025). "The miR-944/FZD7 axis attenuated doxorubicin resistance and reduced tumor growth in colorectal cancer when the circular RNA circCSPP1 was knocked down." (PMID 35127342, 2022). "Wnt/β-catenin signaling is activated aberrantly in many human cancers, and FZD7 is frequently up-regulated in a variety of cancers including breast and colorectal cancer." (PMID 29207657, 2017). "While other published studies have described the role of β-catenin in the regulation of FZD7 promoter activity in colorectal cancer, our study extends these observations to ER-positive and ER-negative breast cancer cells." (PMID 24897117, 2014). "Another study had also shown that FZD7 expression was regulated by β-catenin in colorectal cancer cells." (PMID 24897117, 2014). "FZD7 has also been identified as a potential therapeutic target in hepatocellular and colorectal cancers." (PMID 19874621, 2009). "Hence, ectopic expression of Fzd7 has a profound role in tumorigenesis and is critical for the survival, invasion, and metastatic capabilities of colorectal cancer." (PMID 38322254, 2024). "Colorectal cancer stem cells exhibit enhanced CD44, CD133 and Lgr5 expression; therefore, loss of Fzd7 may initiate tumorigenesis in the colon." (PMID 36691900, 2023). "FZD7 is also a Wnt target gene, relevant in colorectal cancer and normal intestinal epithelium." (PMID 32403323, 2020). "Fzd7 plays an important role in colorectal cancer development and metastasis." (PMID 23209942, 2012). "Additionally, studies have explored the development of inhibitors that specifically target FZD7 and future inhibitors targeting FZD7 may represent another therapeutic approach for colorectal cancer." (PMID 40611274, 2025). "FZD7 mRNA levels in stage II, stage III, and stage IV tumors were significantly higher than in nontumor tissues in 135 primary colorectal cancer (CRC) tissues." (PMID 40171220, 2025).
colon cancer (15 papers, 2008 to 2025). "Knockdown of FZD7 using siRNA was able to inhibit proliferation of human ovarian adenocarcinoma cell lines associated with changes in cell morphology which have also been observed in colon cancer cells." (PMID 27196929, 2016). "FZD7 has a function in canonical signaling, and research has demonstrated that colon cancer cells express this gene at a very high level." (PMID 40171220, 2025). "FZD7 also regulates Wnt/JNK signaling in colon cancer and is, therefore, capable to activate both, Wnt canonical and non-canonical signaling pathways." (PMID 31671889, 2019). "The role of Fzd7 during MET was further supported in experiments using a novel model of tumour morphogenesis termed LIM1836-Mph cells (human colon cancer cells) which go through cycles of EMT and MET in vitro." (PMID 27196929, 2016). "Inhibition of FZD7 using a dominant negative extracellular domain is able to block the growth of human colon cancer cells in vitro and in xenograft experiments with stably transfected SK-CO-1 cells, which harbour mutations to APC." (PMID 27196929, 2016). "Frizzled 7 (Fzd7) is one of important member of Fzd family, previous investigations indicated that Fzd7 regulates invasion of colon cancer, emerging as novel potential target for cancer therapy." (PMID 26744382, 2016). "In this study, we examined the function of FZD7 in survival, invasion and metastatic capabilities of colon cancer cells." (PMID 19773752, 2009). "We previously reported that FZD7 functions as a receptor for the canonical Wnt signalling pathway in colon cancer cells." (PMID 19773752, 2009). "Thirteen shRNA expression vectors harbouring siRNAs against FZD7 were constructed and tested to determine which had the greatest suppressive effect on endogenous FZD7 expression in colon cancer cells." (PMID 19773752, 2009). "We have recently reported that frizzled-7 (FZD7), 1 of 10 members of the FZD gene family, is predominantly expressed in colon cancer cells and is implicated in canonical Wnt signalling in colon cancer cells with APC or CTNNB1 mutations." (PMID 19773752, 2009). "In the present study, we revealed that intracellular cholesterol could promote YAP expression via the FZD7/PCP/RhoA pathway in colon cancer cells." (PMID 33637695, 2021). "Down-regulation of Fzd7 expression inhibits invasion and metastasis of colon cancer cells." (PMID 26744382, 2016). "Subsequent investigations demonstrate that FZD7 is a direct regulatory target of miR-23b and targeted inhibition of FZD7 or miR-23b can significantly reduce migration, growth and angiogenesis in human colon cancer cells." (PMID 27196929, 2016). "Indeed, this was subsequently formally demonstrated by Ueno and colleagues who showed FZD7-mediated vertebrate PCP pathway is involved in colon cancer cell migration." (PMID 27196929, 2016). "In this context, FZD7 might be one of mesenchymal characteristics of colon cancer cells when they metastasise through epithelial–mesenchymal transition." (PMID 19773752, 2009). "In conclusion, we first reported that FZD7 may be important in the survival, invasion and metastatic capabilities of colon cancer cells, at least partly, through expression of c-Jun, phosphorylation of c-Jun and JNK, and activation of RhoA." (PMID 19773752, 2009). "To address this hypothesis, we attempted to reveal a function of FZD7 in the survival, invasion and metastatic capabilities of colon cancer cells with the use of newly prepared and selected siRNAs against FZD7." (PMID 19773752, 2009). "On the other hand, nuclear β-catenin was very low in migrating LIM1836-Mph cells, however FZD7 shRNA could also inhibit migration of these cells suggesting Fzd7 mediates non-canonical signalling of migrating colon cancer cells." (PMID 27196929, 2016). "It was clearly decreased with FZD7_siRNA transfection, suggesting that FZD7 may be a receptor for the non-canonical Wnt/JNK signalling pathway in colon cancer cells." (PMID 19773752, 2009).
colon cancer (continued). "Although there is a report that conditional ROCK activation of colon cancer cells induced in vitro motility and in vivo tumour cell dissemination in nude mice, the relation of FZD7 with non-canonical signals in CRC cells remains unknown." (PMID 19773752, 2009).